ROCK1 (Rho associated coiled-coil containing protein kinase 1)
Diseases named in the same sentence as ROCK1 in open-access papers (continued):
Sharing a sentence is not in itself a finding about the gene and the disease.
gastric cancer (36 papers, 2013 to 2026). A primary or metastatic malignant neoplasm involving the stomach. "The rho-associated, coiled-coil-containing protein kinase 1 ROCK1 has been identified as the target of miR-135a in gastric cancer cells." (PMID 36147505, 2022). "In the present study, we found that ROCK1 is a target of miRNA-135a in gastric cancer and its expression is positively associated with LN metastasis in EGC patients." (PMID 24465504, 2014). "Furthermore, we also identified a new target gene of miRNA-135a, ROCK1, which was associated with LN metastasis in gastric cancer." (PMID 24465504, 2014). "The transcription factor TFAP2C is reported to upregulate the expression of ROCK1 in colorectal cancer, and another transcription factor, ONECUT2, activates transcription of ROCK1 in gastric cancer." (PMID 40419128, 2025). "Similar results were reported in breast and gastric cancer cells, where it was seen that Nrf2/Keap1 promoted cell migration by upregulating the RhoA/ROCK1 pathway." (PMID 33441941, 2021). "In fact, NEAT1 was shown to sponge hsa-miR-335-5p, releasing ROCK1 from its suppression, which promotes cell proliferation, migration, and invasion in gastric cancer." (PMID 35008626, 2021). "Upregulation of NORAD promoted gastric cancer progression by activating the RhoA/ROCK1 axis, which correlated with poorer prognosis." (PMID 33292272, 2020). "In summary, we confirmed that DADS reduces the expression of Rac1, Pak1 and Rock1 in gastric cancer MGC803 cells." (PMID 26871290, 2016). "For example, Zheng and colleagues showed that miR-148a downregulates ROCK1 to suppress tumor cell invasion and metastasis in gastric cancer." (PMID 25912304, 2015). "Rac1, Pak1 and Rock1 are indicators related to gastric cancer invasion and metastasis, but few reports discuss all three kinds of protein in research on gastric cancer invasion and metastasis." (PMID 23298303, 2014). "In gastric cancer, ROCK1 has been positively correlated with LN metastasis and TNM stage, and is involved in miRNA-148a-induced suppression of gastric cancer cell migration and invasion." (PMID 24465504, 2014). "The correlation among the expression of Rac1, Pak1 and Rock1 in gastric cancer was analyzed using Spearman's rank correlation." (PMID 23298303, 2014). "Taken together, neogenin-1 appears to regulate ROCK1 activation leading to gastric cancer cell migration and invasion." (PMID 24930499, 2014). "In vitro experiments also showed that ROCK1 is involved in gastric cancer cell motility and invasion." (PMID 24465504, 2014). "In the present study, immunohistochemistry and a tissue microarray were used in the detection of Rac1, Pak1 and Rock1 protein expression levels in gastric cancer cells, intraepithelial neoplasia and normal tissues." (PMID 23298303, 2014). "The correlation of Rac1, Pak1 and Rock1 expression in gastric cancer was analyzed using Spearman's rank correlation, and the expression of the three groups in gastric cancer was positively correlated (r = 0.555, P < 0.05)." (PMID 23298303, 2014). "The aim of this study was to investigate the expression and clinical significance of Rac1, Pak1 and Rock1 in gastric carcinoma." (PMID 23298303, 2014). "Pak1 expression levels in normal gastric tissue, intraepithelial neoplastic tissues and gastric carcinoma were 20, 35 and 60 percent, respectively, whereas Rock1 expression was 16, 28 and 58 percent, respectively." (PMID 23298303, 2014). "The positive expression rates of Rac1, Pak1 and Rock1 in normal tissue, intraepithelial neoplastic tissues and gastric carcinoma showed an increasing trend (P < 0.05)." (PMID 23298303, 2014). "Rac1, Pak1 and Rock1 expression in 158 cases of gastric carcinoma were investigated via immunohistochemical staining and clinical analysis." (PMID 23298303, 2014). "Positive rates of Rac1, Pak1 and Rock1 expression in normal tissue, dysplasia and gastric carcinoma show an increasing trend and are correlated with tumor lymph node metastasis and TNM stage." (PMID 23298303, 2014).
gastric cancer (continued). "The overexpression of ROCK1 can promote proliferation, invasion and migration in gastric cancer." (PMID 37007126, 2023). "It is known that miR-148a can directly target ROCK1 in gastric cancer and NSCLC." (PMID 34271873, 2021). "We also found that mRNA expression levels of CDH1, CDKN1A, and EP300 were significantly reduced while those of RhoA, ROCK1, ROCK2, PIK3CA, and CCND1 were significantly increased in gastric cancers with reduced or loss of NKX6.3 expression compared to those in NKX6.3 positive cases." (PMID 30514953, 2018). "In addition, expression levels of CDH1, CDKN1A, and EP300 were reduced while expression levels of RhoA, ROCK1, ROCK2, PIK3CA, and CCND1 were increased in gastric cancer tissues with reduced or loss of NKX6.3 expression." (PMID 30514953, 2018). "In addition, we have found that the increased expression of Rac1, Pak1 and Rock1 in primary gastric cancer is correlated with lymph node metastasis, clinical stage and poor prognosis." (PMID 26871290, 2016). "In conclusion, we have identified miRNA-135a as a new prognostic biomarker for LN metastasis in patients with EGC and demonstrated that miRNA-135a suppressed gastric carcinogenesis (i.e., proliferation, EMT, and metastasis in gastric cancer cell lines) by targeting ROCK1." (PMID 24465504, 2014). "In gastric cancer cell lines, miRNA-135a and ROCK1 showed an opposing expression pattern." (PMID 24465504, 2014). "Although these findings require validation in other independent patients groups, they suggest that miRNA-135a and its target gene ROCK1 may be a new biomarker and therapeutic target for gastric cancer with LN metastasis." (PMID 24465504, 2014). "Rac1, Pak1 and Rock1 expression in gastric cancer was positively correlated (r = 0.555, P < 0.05)." (PMID 23298303, 2014). "Further, ROCK1 inhibitor promoted apoptosis in gastric cancer cells." (PMID 24465504, 2014). "The expression of Rac1, Pak1 and Rock1 in normal epithelium and intraepithelial neoplastic epithelium was weakly positive or positive; however, a large number of positively stained cells were heterogeneously distributed in the gastric carcinoma tissues." (PMID 23298303, 2014). "They further found that Rho-associated, coiled-coil containing protein kinase 1(ROCK1), which might be a target of miR-148a, was involved in miR-148a-induced suppression of gastric cancer cell migration and invasion." (PMID 23683438, 2013). "Therefore, we propose that in the treatment of gastric cancer, the combination of RhoA/ROCK1 inhibitors may enhance the tumor‐killing effect of OXA." (PMID 39392399, 2024). "Rac1, Pak1 and Rock1 expression in gastric cancer is closely related with the degree of gastric cancer lymph node metastasis and TNM stage and they play an important role in the invasion and metastasis of gastric cancer and might be key biological markers for invasion and metastasis." (PMID 23298303, 2014). "Moreover, ROCK1 increases gastric cancer cell migration and invasion, and the inhibition of ROCK1 induces apoptosis in gastric cancer cells, suggesting that neogenin-1 increases the activation of ROCK1 and, in turn, promotes gastric cancer cell survival and motility." (PMID 24930499, 2014). "We found that ROCK1 might be a target gene of miRNA-135a because inhibition or suppression of ROCK1 has been reported to promote apoptosis and to suppress migration, invasion, and proliferation of cancer cells including those of gastric cancer." (PMID 24465504, 2014). "Rac1, Pak1 and Rock1 may be important biomarkers of gastric carcinoma invasion and metastasis." (PMID 23298303, 2014). "Our findings indicate that ASTX can suppress H. pylori-induced gastric cancer progression by inhibiting cytoskeleton reorganization and reducing cell motility through downregulation of c-MET, EGFR, PI3KC2, PLCγ1, Cdc42, and ROCK1." (PMID 32679742, 2020).
gastric cancer (continued). "In conclusion, ASTX can suppress H. pylori-induced gastric cancer progression by inhibiting cytoskeleton reorganization and reducing cell motility through downregulation of c-MET, EGFR, PI3KC2, PLCγ1, Cdc42, and ROCK1." (PMID 32679742, 2020). "Therefore, ROCK1 may be involved in miRNA-135a-suppressed gastric cancer metastasis." (PMID 24465504, 2014). "Y27632, a selective small inhibitor of both ROCK1 and ROCK2, was combined with apatinib, and its efficacy was evaluated, wherein it can reduce hypertension induced by apatinib treatment in gastric cancer mice and weaken the activation of the RhoA/ROCK pathway by apatinib and a high-salt diet (HSD)." (PMID 35811723, 2022). "To establish whether neogenin-1 induced gastric cancer cell migration and invasion through ROCK1 activation, we over-expressed neogenin-1 in SNU-668 cells and decreased the expression of ROCK1 by ROCK1 siRNA." (PMID 24930499, 2014). "Results showed that expression levels of NKX6.3, CDH1, CDKN1A, and EP300 were decreased while expression levels of NFκB p65, AICDA, CBFβ, APOBEC3A, APOBEC3B, RhoA, ROCK1, ROCK2, PIK3CA, and CCND1 were increased in CagA positive gastric cancers compared to those in CagA negative cases." (PMID 30514953, 2018).
prostate carcinoma (33 papers, 2011 to 2024). A carcinoma that arises from epithelial cells of the prostate gland. "Genetic variants in RhoA and ROCK1 genes have been suggested as susceptibility factors for prostate cancer development." (PMID 32872192, 2020). "In summary, the results of our study demonstrate that up-regulation of ROCK1 is common in prostate cancer and is associated with tumor aggressiveness and poor prognosis." (PMID 31557128, 2019). "A clinically relevant role of ROCK1 overexpression in prostate cancer is also consistent with reports from several other cancer types, where high ROCK1 expression was associated with tumor aggressiveness." (PMID 31557128, 2019). "The results of this study demonstrate that overexpression of ROCK1 is associated with adverse tumor features and early biochemical recurrence in prostate cancer." (PMID 31557128, 2019). "Genetic variants of RhoA and ROCK1 genes have been suggested as susceptibility factors for prostate cancer development." (PMID 31557128, 2019). "Taken together, the results in our present study provided new insight into genetic variants in RhoA/ROCK1 signaling pathway and their function in prostate cancer." (PMID 28184030, 2017). "Our study is the first to clarify the relations of genetic variants of RhoA and ROCK1 genes with development, progression and prognosis of prostate cancer." (PMID 28184030, 2017). "Moreover, the up-regulation of ROCK1 was associated with genetic instability as well as poor clinical prognosis of prostate cancer." (PMID 39455522, 2024). "Background and objectives: Overexpression of the cytoskeleton-modulating kinase ROCK1 has been associated with unfavorable outcome in many cancers, but its impact in prostate cancer is largely unknown." (PMID 31557128, 2019). "Association between ROCK1 staining and prostate cancer phenotype in all cancers." (PMID 31557128, 2019). "Increased ROCK1 expression was associated with TMPRSS2:ERG fusion positive prostate cancers." (PMID 31557128, 2019). "Prostate cancer with high ROCK1 expression was markedly related to advance tumor stage, high classical and quantitative Gleason grade, positive nodal stage, positive surgical margin, and high preoperative PSA level." (PMID 36197602, 2022). "For example, miR-146a is downregulated in androgen-independent prostate cancer tissues, and high expression of miR-146a induces apoptosis by inhibiting ROCK1 expression via targeting of the 3′ UTR." (PMID 35075115, 2022). "The supernatant from these cells was exposed to a prostate cancer cell line, where down-regulation of ROCK1 was again observed and cell proliferation was reduced." (PMID 32528954, 2020). "Immunohistochemistry staining presented higher ROCK1 levels in prostate cancer than in the normal epithelium." (PMID 32872192, 2020). "Later studies found that circPSMC3 inhibited cell proliferation of nasopharyngeal carcinoma and prostate cancer by down‐regulating ROCK1 and DGCR8, respectively." (PMID 32808450, 2020). "In prostate cancer, increased ROCK1 expression has been defined as an early biomarker for poor prognosis due to its association with genetic instability in tumor cells." (PMID 32554853, 2020). "We report that RhoBTB1 depletion increases prostate cancer cell invasion and induces elongation in Matrigel, a phenotype similar to that induced by depletion of ROCK1 and ROCK2." (PMID 31431478, 2019). "That ROCK1 staining was generally higher in cancers than in tumor adjacent normal prostatic tissue argues for a role of ROCK1 up regulation in prostate cancer development." (PMID 31557128, 2019). "The molecular database attached to our TMA allowed us to compare ROCK1 expression with other important molecular alterations occurring in prostate cancer." (PMID 31557128, 2019). "One recent study on 56 prostate cancers and adjacent normal tissue reported a higher level of ROCK1 protein expression in tumor glands as compared to normal tissues." (PMID 31557128, 2019).
prostate carcinoma (continued). "The association with unfavorable tumor phenotype and poor clinical outcome in our patients argues for a role of ROCK1 overexpression in prostate cancer progression." (PMID 31557128, 2019). "ROCK1 is androgen responsive, inhibits apoptosis and promotes cell motility and proliferation in prostate cancer cells." (PMID 31557128, 2019). "In prostate cancer, Kroiss and his colleagues also demonstrated that miR-135a decreased prostate cancer cell migration and invasion through downregulating ROCK1 and ROCK2." (PMID 27323416, 2016). "In the present study, we found that radiation exposure decreased the expression of ROCK1 in a dose-dependent way in prostate cancer cells." (PMID 24504141, 2014). "Previous experimental work have already shown that miR-146b and miR-206 are prostate cancer related miRNAs and targeting ROCK1 and HDAC4, respectively." (PMID 24267745, 2013). "In prostate cancer cells ROCK1, one of the key kinases for the activation of the hyaluronan, was found to be targeted by miR-146a." (PMID 22453030, 2012). "ROCK-1, which is activated by activated RhoA, promotes cell invasion and motility in prostate cancer and colorectal carcinoma cells." (PMID 21119662, 2011). "Similarly, in the targeted treatment of prostate cancer with nintedanib, prostate cancer cells acquired resistance to nintedanib and survived by activating entosis formed by the upregulation of E-cadherin and ROCK1/2 through the PI3K/CDC42 signaling pathway." (PMID 37637068, 2023). "In prostate cancer, suppressing RhoA/ROCK1 signaling inhibits cellular proliferation and EMT." (PMID 34486491, 2021). "In prostate cancer, miR-135a repressed cell migration and proliferation by downregulating matrix metallopeptidase 11 (MMP11), rho associated coiled-coil containing protein kinase 1 (ROCK1), ROCK2, RB associated KRAB zinc finger (RBAK) and STAT643,60,64." (PMID 32944391, 2020). "In one form of prostate cancer it was found that miR-146a was down-regulated and when it was exogenously expressed in a prostate cancer cell line it reduced the expression of its target gene, ROCK1, by almost 80% and consequently reduced cell proliferation, invasion, and metastasis." (PMID 32528954, 2020). "Anti-cancer drugs specifically targeting ROCK1 may thus be particularly efficient in prostate cancer." (PMID 31557128, 2019). "The data from our study suggest a high importance of ROCK1 for prostate cancer biology." (PMID 31557128, 2019). "The data of this study suggest that ROCK1 expression may represent a potentially clinically useful prognostic marker in prostate cancer." (PMID 31557128, 2019). "A study published in PNAS surveyed endothelial cells (ECs) of transgenic mice bearing prostate adenocarcinoma and indicated that high level of baseline activity of RhoA and ROCK1 might give rise to aberrant behaviors of prostate cancer ECs." (PMID 28184030, 2017). "The contribution of genetic variants in RhoA and ROCK1 genes towards prostate cancer risk has not been reported before." (PMID 28184030, 2017). "Additionally, Kroiss had demonstrated that miR-135a decreased prostate cancer cell migration and invasion through downregulating ROCK1 and ROCK2." (PMID 27323416, 2016). "ROCK1 is a target of several miRNAs in various cancers including miRNA-584 in renal cell carcinoma, miRNA-335 in neuroblastoma, and miRNA-146a in prostate cancer." (PMID 24465504, 2014). "Moreover, ROCK1 measurement, either alone or in combination might be of clinical utility in prostate cancer." (PMID 31557128, 2019). "The significant up-regulation of ROCK1 in cancers harboring the TMPRSS2:ERG fusion fits with an earlier report describing increased expression of ROCK’s upstream regulator Rho guanine diphosphate dissociation inhibitor beta (ARHGDIB) in ERG positive prostate cancers." (PMID 31557128, 2019). "Therefore, it was suggested that ROCK1 suppression could aid in reducing the metastatic potential of prostate cancer cells." (PMID 24504141, 2014).
prostate carcinoma (continued). "Transfection of miR-146a in an androgen-independent prostate cancer cell line resulted in a marked reduction of cell proliferation, invasion and metastasis to bone marrow, an effect seemingly mediated by the targeting of ROCK1, one of the key kinases for the activation of hyaluronan." (PMID 22453030, 2012). "Another example is miR135a which targets both ROCK1 and ROCK2 as well as numerous genes involved in cellular movement, cellular assembly/organization, and cell morphology in prostate cancer cells." (PMID 26725045, 2016). "It has been reported that ROCK-1 is over-expressed in brain tumour and related to metastasis in rat MM1 hepatoma cells, bladder, lung and prostate cancer." (PMID 21119662, 2011). "In addition, microRNA‐122 inhibited the cell viability of prostate cancer cells via down-regulating ROCK2, and ROCK1 or ROCK2 knockdown in DU145 or PC-3 cells inhibited cell proliferation." (PMID 39455522, 2024). "In prostate carcinoma, POU3F3 promotes cancer cell proliferation by upregulating ROCK1." (PMID 35201451, 2021). "Besides, Rho/ROCK1 pathway was found to regulate membrane androgen receptor-induced apoptosis in both LNCaP and DU145-prostate cancer cells." (PMID 28184030, 2017).